AR (androgen receptor)
Diseases named in the same sentence as AR in open-access papers (continued):
Sharing a sentence is not in itself a finding about the gene and the disease.
prostate carcinoma (continued). "Central to this process is the dysregulation of androgen receptor (AR) signaling, which is crucial for the growth and survival of prostate cancer cells." (PMID 39272896, 2024). "The current main treatment for AR-null prostate cancer is platinum-based chemotherapy, which is rapidly becoming resistant." (PMID 38254880, 2024). "To test another xenograft model in humanized mice, we relied on the VCaP castration-resistant-xenograft model, which mimics the natural history of prostate cancer, with short-term responses to both castration and AR antagonism." (PMID 38820127, 2024). "The inhibitory effect of HLT-101 on AR signaling was confirmed in rat tissues and LNCaP cells, an androgen-dependent prostate cancer cell line." (PMID 37994101, 2024). "To gain a better understanding of the significance that D2‐mediated oligomerization has in cells, we analyzed the impact of this feature of the DTX3L‐PARP9 complexes in prostate cancer cells that express the AR (PC3‐AR)." (PMID 38511494, 2024). "Ligand binding induces conformational changes in the AR, leading to its nuclear translocation and activation of target gene transcription, representing essential processes for prostate cancer progression." (PMID 39335158, 2024). "NSD2 contributes to AR cistrome reprogramming during prostate cancer progression, and its degradation via a novel PROTAC reduces prostate cancer cell viability in vitro." (PMID 39251788, 2024). "Prostate cancer cells rely on AR, HOXB13 and FOXA1-regulated transcriptional programs for tumor progression and resistance to anti-androgens." (PMID 38730575, 2024). "Prostate cancer progression is associated with increased interaction between ALDH1A1 and the androgen receptor (AR) and RAR." (PMID 38928275, 2024). "Prostate cancers driven by androgen receptor (AR) or FOXA1 are more sensitive to SWI/SNF degraders than cancers in which subunits of the SWI/SNF complex are mutated." (PMID 39697230, 2024). "In prostate cancer, O-GlcNAcylation occurs on the androgen receptor (AR) protein at the Thr-80 residue next to the Ser-81 phosphorylation site, which leads to stabilization, nuclear translocation, and transactivation of AR." (PMID 39178944, 2024). "Background/Objectives: Abiraterone acetate, apalutamide, darolutamide, and enzalutamide, which make up the androgen receptor axis-targeted therapies (ARATs) drug class, are commonly used in the management of prostate cancer." (PMID 39409956, 2024). "Given the importance of the AR in normal cell growth and its critical role in the progression of prostate cancer, we investigated potential cell morphology changes induced by treatment with the synthetic androgen R1881 on androgen-sensitive LNCaP cells." (PMID 39858418, 2024). "First, we opted to investigate AR-mediated transcription using the LNCaP prostate cancer cell line, a well-established androgen-dependent PCa model." (PMID 39489778, 2024). "Since long-term intensive inhibition of AR signaling renders prostate cancer lethal and AR-indifferent lineages, it is crucial to eliminate them before this transformation occurs." (PMID 38201308, 2024). "The androgen receptor (AR) is a validated target for the prevention and treatment of prostate cancer (PCa), and androgen deprivation via pharmaceutical treatment induces remission of the primary form of PCa." (PMID 39479643, 2024). "In this study, the efficacy of bicalutamide addition, a second-generation AR antagonist that is widely used in prostate cancer, to conventional chemotherapy (doxorubicin and docetaxel) used in breast cancer has been evaluated for IMC and IBC." (PMID 39063165, 2024). "Collectively, these data reveal the potential of combining CDKI-73 with a BRD4 inhibitor as a novel treatment for aggressive prostate cancer, including both AR-driven and AR-independent disease states." (PMID 39117800, 2024). "Mechanistically, menin promotes AR-positive prostate cancer growth through the activation of AR signaling." (PMID 39336822, 2024).
prostate carcinoma (continued). "Concerning CREB3L2, it collaborates with the androgen receptor to regulate the ER-to-Golgi trafficking pathway to drive prostate cancer progression." (PMID 39337607, 2024). "This conclusion was substantiated by our examination of PSMD1 and AR signalling components in a sample of six prostate cancer patients exhibiting elevated GOLM1 expression." (PMID 39470578, 2024). "Androgens and androgen receptors (AR) are involved in the early tumorigenicity and androgen refractory disease of prostate cancer (PCa)." (PMID 39130630, 2024). "Ultimately, it was discovered that the WWL0245 caused an arrest in the cell cycle at the G0/G1 phase and triggered programmed cell death in prostate cancer cells that express AR." (PMID 38389844, 2024). "These drugs effectively inhibited the proliferation of an androgen receptor (AR)-positive prostate cancer cell line, with the most potent compound, PB16, exerting its effects in the sub-micromolar range." (PMID 38390898, 2024). "Several signal transduction pathways activated by testosterone via AR-independent mechanisms, including c-Src, have been reported in prostate cancer cells." (PMID 37991884, 2024). "As prostate cancer research continues to uncover the crucial roles of AR-Vs in treatment resistance and disease progression, the urgency to develop effective interventions becomes evident." (PMID 38201308, 2024). "For instance, growing the prostate cancer LNCaP cells in castrated mice and treating them with the AR inhibitor enzalutamide shows that elevated glucocorticoid receptor (GR) expression is involved in the resistance process." (PMID 38255778, 2024). "As a p300 HAT inhibitor, B026 was approximately 30-fold superior to A485, inhibiting cell growth in various hematological and androgen receptor positive (AR+) prostate cancers." (PMID 39407454, 2024). "Cancer-associated fibroblast infiltration has been associated with disease progression in prostate cancer, whilst high MYC TF activity induces low AR TF activity to drive disease progression and castration resistance in prostate cancer." (PMID 39574035, 2024). "The search for the first generation of AR antagonists began in the late 1960s and early 1970s, leading to the FDA approval of three first-generation AR antagonists: flutamide, nilutamide, and bicalutamide for prostate cancer treatment." (PMID 38339414, 2024). "The AR is a major driver of prostate cancer progression and treatment response and AR signaling inhibitors are commonly used for patients with mCRPC30,31." (PMID 38396008, 2024). "Tumorigenesis and progression of prostate cancer (PCa) are indispensably dependent on androgen receptor (AR)." (PMID 38918720, 2024). "GIGGLE analysis revealed a significant overlap between H3K27ac lost sites and the cistromes of key transcriptional and epigenetic regulators of prostate cancer, including AR, FOXA1 and HOXB13, supporting their functional relevance." (PMID 39117800, 2024). "Identification of E2F8 as a novel regulator of AR biogenesis and transcription provides a new therapeutic target in castration‐resistant prostate cancer." (PMID 38605607, 2024). "Our results suggest that ROR1 is an important driver of cancer aggression in ARneg-AI prostate cancer that exhibits castration resistance and lacks a targetable AR." (PMID 39000112, 2024). "Prostate cancer progression is driven by androgen receptor (AR) activity, which is a target for therapeutic approaches." (PMID 39253786, 2024). "The androgen receptor (AR) signaling pathway, activated by androgens, is the primary driver of prostate cancer development and progression." (PMID 39770110, 2024). "Since the androgen receptor (AR) and its signaling cascades are prime targets in prostate cancer therapy, we focused on the effect of MA on AR regulation." (PMID 38605607, 2024). "The menin–MLL complex is a co-activator of AR signaling in prostate cancer, with menin recognizing the N-terminal domain of AR." (PMID 39336822, 2024).
prostate carcinoma (continued). "TRIM24 plays a pivotal role in driving the proliferation of castration-resistant prostate cancer cells, aligning with the concept that AR co-activators sustain AR-mediated signaling during low hormone availability." (PMID 39160596, 2024). "AHR’s role in prostate cancer is complex, particularly when considering its interaction with AR signaling." (PMID 39600743, 2024). "In particular, several mechanisms are involved in the anti-prostate cancer activity of the molecules, including the inhibition of the androgen receptor axis and targeting of cancer stem cells." (PMID 39062777, 2024). "Therapy based on inhibition of androgen and androgen receptor has always been the first-line treatment of prostate cancer." (PMID 39097593, 2024). "Hormonal therapies that block androgen generation or directly inhibit the androgen receptor are major therapies for patients with advanced prostate cancer." (PMID 38256933, 2024). "It explains genital abnormalities and infertility in LEOPARD syndrome patients, and AR upregulation in prostate cancer." (PMID 38965223, 2024). "To add rigor to our study, we expanded our AR activity analysis to the TCGA prostate cancer dataset (EA: n = 270 T, 36 NT; AA: n = 43 T, 6 NT)." (PMID 38566104, 2024). "MA is expected to be used in combination with ADT for the treatment of AR-positive prostate cancer patients." (PMID 39624845, 2024). "The present resultsindicate that one of the azolato-bridged complexes, 5-H-Y, effectively inhibits prostate cancer cell proliferation by bindingto AR, as well as by inducing apoptosis after DNA-binding." (PMID 39258898, 2024). "Regarding cancer, studies have indicated that using FK506, which binds to the FK1 domain of FKBPs, or MJC13, an inhibitor of FKBP52, to treat prostate cancer can inhibit cell proliferation and AR activity." (PMID 38786025, 2024). "The androgen receptor (AR) regulates transcription, genomic stability and DNA repair and is of clinical relevance in prostate cancer as a therapeutic target used in androgen deprivation therapy." (PMID 38730670, 2024). "ER was crucial in the initiation and spread of breast and ovarian cancer while AR exerted important roles in prostate cancer." (PMID 38347836, 2024). "PHF8 influences prostate cancer progression and resistance mechanisms by integrating into the androgen receptor signaling axis, a key pathway in castration-resistant prostate cancer (CRPC)." (PMID 38813086, 2024). "Prostate cancer is dependent on androgen receptor (AR) signaling, and androgen deprivation therapy (ADT) has proven effective in targeting prostate cancer." (PMID 38698344, 2024). "FOXA1 is crucial for the chromatin binding of the androgen receptor (AR) in both normal prostate epithelial cells and the luminal subtype of prostate cancer (PCa)." (PMID 38851846, 2024). "Overall, the experimental results suggest that adenoviral vaccines targeting AR and AR-Vs hold significant promise for the treatment of prostate cancer." (PMID 39591176, 2024). "The androgen receptor (AR) is known to play a key role in the pathogenesis of prostate cancer and can be activated by ligand testosterone or 5α-dihydrotestosterone (DHT)." (PMID 39598525, 2024). "Androgen receptor (AR) and estrogen receptor alpha (ERα) are known as oncogenic factors that control super enhancer genes in prostate cancer and breast cancer, respectively." (PMID 38658705, 2024). "Early reports have been inconclusive on the function of the androgen receptor in cribriform architecture prostate cancers, although it has been reported that IDC-P contains androgen-indifferent cells as part of its heterogeneity." (PMID 40129601, 2024). "ARV-110 is designed to target metastatic castration-resistant prostate cancer (mCPRC) by the highly selective knockdown of AR subsequently suppressing PSA expression." (PMID 39144725, 2024).
prostate carcinoma (continued). "In prostate cancer, silencing androgen receptor mRNA delays the formation of SGs induced by androgen receptor pathway inhibition (ARPI) stress." (PMID 39193335, 2024). "Prostate cancer (PCa) patients with elevated level of androgen receptor (AR) correlate with higher metastatic incidence." (PMID 39149855, 2024). "By clustering them into three phenotypes according to AR activity and NE activity, we found that FGF signaling is significantly activated in AR-null prostate cancer cells, including DNPC and NEPC." (PMID 38254880, 2024). "Primary prostate cancer is largely driven through androgen signalling via interactions with the androgen receptor (AR) and is commonly therapeutically managed with androgen deprivation therapies (ADT)." (PMID 39272811, 2024). "For instance, inhibiting endosome recycling by the anti-malarial small molecule primaquine in prostate cancer cells reduced the expression of androgen receptor, modulated lysosome degradation kinetics, and resulted in decreased cell survival independently." (PMID 39796673, 2024). "AR signaling is critical for the viability of AR-expressing prostate cancer cells (Huang & Tindall 2002, Dehm & Tindall 2006)." (PMID 38410785, 2024). "Independent of promoting mitotic arrest, MSAs can suppress the nuclear accumulation of androgen receptor, which is the driving force for prostate cancer cell growth and progression." (PMID 38310601, 2024). "Specifically, their investigation into androgen deprivation therapy highlighted its potential to enhance the effectiveness of ICIs in prostate cancer by modulating androgen receptor activity and improving T-cell function." (PMID 38539486, 2024). "This review investigates the emerging significance of the aryl hydrocarbon receptor (AhR) in prostate cancer, focusing on its role in modulating androgen receptor (AR) signaling and its potential as a therapeutic target." (PMID 39184676, 2024). "The results collectively show that MDM2 inhibition markedly enhances the migration of prostate cancer cells, which are likely mediated by the positive effect of MDM2i on AR, AR-V7, and TM4SF3 proteins." (PMID 38410785, 2024). "Preclinical evidence has suggested an interplay between the androgen receptor, which largely drives the growth of prostate cancer cells, and poly(ADP-ribose) polymerase." (PMID 38049622, 2024). "In conclusion, DPYSL5 plays a critical role in regulating prostate cancer cell plasticity, and we propose the AR/DPYSL5/EZH2/PRC2 axis as a driver of t-NEPC progression." (PMID 38238517, 2024). "Prostate cancer cells depend on androgens for growth and survival, with the androgen receptor (AR) being pivotal in mediating androgen-dependent transcriptional processes." (PMID 39199550, 2024). "We identified E2F8 as a reliable molecular target of MA and a novel regulator of AR transcription in prostate cancer." (PMID 38605607, 2024). "Prior studies have indicated SNRPE’s role in promoting cell growth and advancing high-grade prostate cancer by controlling the expression of the androgen receptor [22740892]." (PMID 39726597, 2024). "To assess responses of prostate cancer cells to platinum-based cytotoxic drugs, we utilized three cell lines with different AR status." (PMID 38218884, 2024). "WWL0245 exhibited significant effectiveness in promoting the BRD4 degradation in prostate cancer cell lines that express AR." (PMID 38389844, 2024). "UBX‐390 is presented as an optimized AR degrader with remarkable potential for treating castration‐resistant prostate cancer." (PMID 38958553, 2024). "A similar result was obtained from a Chip-Seq study that AZGP1 acted as an androgen-responsive gene to mediate proliferation and metastasis of prostate cancer cell via the contribution of androgen receptor." (PMID 38874510, 2024).
prostate carcinoma (continued). "The combined effect of GT+Q+Arc was associated with an increased modulation of multiple critical signaling pathways/events involved in prostate cancer carcinogenesis, including the AR and PI3K/Akt pathways and angiogenesis." (PMID 38254705, 2024). "It is also shown that AR gene is the direct target of β-catenin/TCF/LEF transcriptional complex in prostate cancer cells." (PMID 38531859, 2024). "In the case of AR positive prostate cancer cytoplasmic filamin A is cleaved and the 90 kDa fragment translocates to the nucleus, where it inhibits AR activity, resulting in decreased metastatic potential." (PMID 38958472, 2024). "The androgen axis and its nuclear receptor, the androgen receptor (AR), play a pivotal role in the carcinogenesis of prostate cancer and the progression of the disease." (PMID 39771106, 2024). "Our observations provide a rationale to measure gene expression changes in TGF-β, IDH1, and cell cycle pathways, in prostate cancer of AA and EA men treated with AR inhibitors." (PMID 38566104, 2024). "The polymorphic CAGn locus in exon 1 of the AR gene is associated with several diseases, including spinal and bulbar muscular atrophy (SBMA), prostate cancer, and male infertility." (PMID 39596257, 2024). "Enzalutamide (ENZ) is an androgen receptor signaling inhibitor that both inhibits the proliferation and induces the death of prostate cancer cells." (PMID 38675118, 2024). "For instance, in vitro studies using prostate cancer cell lines have demonstrated that activation of AhR with ligands such as dioxins and certain polycyclic aromatic hydrocarbons leads to increased AR transcriptional activity and tumor cell proliferation." (PMID 39184676, 2024). "This reduction in PSA expression highlights silibinin’s potential role in disrupting AR signaling pathways, making it a viable therapeutic agent for managing prostate cancer, including castration-resistant prostate cancer (CRPC)." (PMID 39199550, 2024). "Studies indicate that interplay or dysregulation of signalings between β-catenin and androgen receptor (AR) can contribute to the advanced and androgen-independent growth of prostate cancer." (PMID 38531859, 2024). "The AR signaling pathway remains a pivotal drug target for the treatment of both hormone-sensitive and castration-resistant prostate cancer." (PMID 38339414, 2024). "Presently, the main focus of prostate cancer treatments lies in targeting androgen synthesis and/or androgen receptor (AR) signaling." (PMID 38318112, 2024). "In prostate cancer cells, similar interactions between AR and STAT5a/b signaling were shown and in hepatocellular cancer, CBG expression is regulated via the pioneer factors FOXA1 and the estrogen receptor, potentially underlying sex differences in CBG." (PMID 39240718, 2024). "The androgen receptor (AR), a ligand-dependent transcription factor, plays a key role in regulating prostate cancer (PCa) growth." (PMID 39676172, 2024). "Menin promotes the growth of androgen receptor (AR)-positive prostate cancer cell lines, with multiple groups showing that knocking down menin in human AR-positive prostate cancer cell lines reduces proliferation and tumor xenograft growth." (PMID 39336822, 2024). "These include genes such as DANCR, DRAIC, PCAT29, PCAT19, and PCAT14, all of which have been shown to be regulated by the AR, and are important regulators of prostate cancer cell proliferation, division, migration, and invasion." (PMID 38396008, 2024). "We find that gene expression of several androgen receptor (AR) target genes, including TRIM63, are inversely associated with DNA methylation only in prostate cancer from AA men." (PMID 38566104, 2024). "Orgasmic suppression treatment (ADT), upon which the androgen receptor pathway is focused, is the primary treatment dealing with men who have progressed to advanced stages of prostate cancer." (PMID 39512820, 2024).